CRBN (cereblon)
Diseases named in the same sentence as CRBN in open-access papers (continued):
Sharing a sentence is not in itself a finding about the gene and the disease.
cancer (continued). "Higher expression of CRBN mRNA was observed in cancer cell lines originating from blood compared to solid tissues, suggesting that hematological cancers may respond better to IMiDs." (PMID 36986673, 2023). "The efficacy of IMiD-PROTACs may vary among different types of cancer, due to variations in CRBN expression." (PMID 36986673, 2023). "Historically, the use of CRBN as an E3 ligase developed from immunomodulatory imide drugs (IMiDs) such as thalidomide, lenalidomide, and pomalidomide that exhibit their anti-cancer and immunosuppressant activity by binding the CRBN subunit of the CRL4ACRBN E3 ligase complex." (PMID 36677746, 2023). "Additionally, many other PROTACs have already been developed or are being developed based on IMiDs recruiting CRBN to target cancer-related proteins, including CDK6, MCL-1/BCL-2, BCL-xL, HDAC6, BTK, BRAF, FKBP12, PARP1, BCR-ABL, FAK, and PD-L1." (PMID 36140200, 2022). "Therefore, the ontology terms and pathways associated with CRBN expression suggested the potential mechanisms by which CRBN expression suppresses cancer." (PMID 33916291, 2021). "Thus, when bound to such IMiDs, CRBN is able to target a number of neo-substrates for degradation, including Ikaros and CK1α, thereby inhibiting cancer growth." (PMID 34489457, 2021). "Most cancer types exhibited a lower CRBN expression compared to normal tissues." (PMID 33916291, 2021). "That might be related to a lower contribution of CRBN expression compared to other factors in LUAD cancer progression." (PMID 33916291, 2021). "Given the multiplicity of metabolic pathways regulated by CRBN, we suggest that CISMs may have important consequences on cancer cell metabolism." (PMID 34834536, 2021). "CRBN mRNA expression was downregulated in various cancer types compared to normal cells." (PMID 33916291, 2021). "Afterward, after examining microarray data in the GENT2 database using the HG-U1333_Plus_2 platform, we found that CRBN mRNA expression was significantly downregulated in some cancer types such as brain, breast, colon, head and neck, kidney, lung, pancreas, skin, thyroid, and tongue." (PMID 33916291, 2021). "Interestingly, CRBN expression decreased according to cancer progression (stage 1, stage 2, stage 3, and stage 4), tumor grade (grade 2, grade 3, and grade 4), and nodal metastasis status (N0 and N1)." (PMID 33916291, 2021). "However, CRBN mRNA expression was generally downregulated in multiple types of cancer compared to their corresponding normal tissues." (PMID 33916291, 2021). "However, CRBN-based PROTACs have several limitations including the remaining activity of immunomodulatory drugs (IMiDs) on Ikaros transcription factors as well as CRBN inactivation as a resistance mechanism in cancer." (PMID 33133483, 2020). "Another issue to be explored in this study is whether CRBN is involved in autophagy activation induced by TLR4, and implicated in cancer progression." (PMID 31620128, 2019). "Having shown that CRBNKO H1299 and CRBNKO MCF7 cells exhibited increases of autophagy activation induced by TLR4 stimulation, we further examined whether CRBN affected the migration and invasion of cancer cells." (PMID 31620128, 2019). "Therefore, depending on the expression level of cereblon protein in the target cell, the therapeutic efficacy of treatment with cereblon-based PROTACs may vary depending on the type of cancer." (PMID 40730655, 2025). "Importantly, these genes that were negatively correlated with CRBN expression may negatively affect the prognoses of these cancer types." (PMID 33916291, 2021). "Loss of CRBN expression in cancer cells is a common problem for CRBN-recruited PROTACs; downregulation of CRBN upregulates AMPK activity, suggesting acceleration of immunogenic cell death in these cancer cells." (PMID 41276688, 2025). "CRBN expression is a critical determinant of the selective cytotoxicity of GSPT1 MGDs in NECs and other cancers with shared transcriptomic features, such as AML." (PMID 40551250, 2025).
cancer (continued). "Thalidomide binds cereblon (CRBN), which chaperones CD147 to form a mature CD147-MCT1 complex that drives cancer progression." (PMID 39776493, 2024). "As well as this, QCA570 and BETd-260, composed of the CRBN E3 ligand and newly screened BET small molecule inhibitors, have also been used for cancer treatment." (PMID 36557960, 2022). "We have listed several representative PROTACs based on CRBN, VHL, MDM2, or cIAP1 E3 ligases, and PROTACs that are undergoing anti-cancer clinical trials." (PMID 36557960, 2022). "This included positive associations between losses in 1p36.32, 3p26.2, 4q35.2, 7p22.3 and 18q23 with the expression of the cancer-related genes CDKN11B, CRBN, IRF2, PRKAR1B and NFATC." (PMID 33945543, 2021). "For example, VHL is frequently lost in certain cancer types, such as RCC; in such cases, a different E3 ligase such as CRBN would be more appropriate." (PMID 33627663, 2021). "Another CRBN-based against BET PROTAC named ARV-825 utilizes the link between OTX015 and E3 ligase CRBN to promote BRD4 degradation, eventually inhibiting the cancer cell progression." (PMID 35006464, 2021). "Binding of IMiDs to Cereblon (CRBN), the substrate receptor of the CRL4CRBN E3 ubiquitin ligase, induces cancer cell death by targeting key neo-substrates for degradation." (PMID 34489457, 2021). "Cereblon (CRBN) is the substrate receptor of the cullin 4-RING E3 ligase complex and has been employed for targeted protein degradation in the treatment of cancers." (PMID 30683842, 2019). "Handa and colleagues identified cereblon (CRBN) and DNA binding protein 1 (DDB1) as binding partners of thalidomide in cancer cell extracts." (PMID 20540792, 2010). "Four co-opted E3 ligases, such as CRBN and MDM2, were highly expressed in over 15 cancer types." (PMID 37845222, 2023). "However, we verified CRBN and CDK9 expression levels in the described cells using the Cancer Cell Line Encyclopedia database." (PMID 35628286, 2022). "Therefore, characterizing the common genes that are correlated with CRBN expression in KIRC, LUAD, and SKCM patients implied the potential pathways of CRBN in carcinogenesis and cancer progression." (PMID 33916291, 2021). "Additionally, CRBN inhibited TRAF6-induced ubiquitination of BECN1 (Beclin 1), and that induced autophagy activation in CRBNKD THP-1, CRBN-knockout (CRBNKO) H1299, and CRBNKO MCF7 cancer cells in response to TLR4 stimulation." (PMID 31620128, 2019). "Moreover, CRBN expression levels may serve as a predictive biomarker for the efficacy of GSPT1 MGDs, providing a basis for precise cancer cell-targeting strategies in GSPT1 MGD-based therapeutics." (PMID 40551250, 2025). "A potential lack of genetic dependency on CRBN in cancer cells as exemplified by the Demeter2 score might explain rapid emergence of resistance in patients." (PMID 38177131, 2024). "The downregulation of CRBN is not the only way that cancer cells may use to decrease the efficacy of IMiD-based degraders." (PMID 36986673, 2023). "However, the expression and role of cereblon in tumorigenicity and tumor progression in a variety of cancer types has not been systematically studied." (PMID 33916291, 2021). "The distribution of the examined SNPs of CRBN gene (rs1672753, rs6768972) was not significantly correlated with such factors as: sex, age, family history of cancer, history of other cancers, type of monoclonal protein, class of light chains, disease stage and patient performance status." (PMID 29844872, 2018). "Furthermore, according to Spearman correlation between GSPT1 and the 10 most frequently utilized E3 ligases, the expression levels of CRBN in various cancer types are not prominent; thus, we predicted the possibility of developing MGDs targeting other E3 ligases in the future." (PMID 41194439, 2025).
tumor (43 papers, 2013 to 2026). "CRBN is closely associated with the proliferation and metabolism of normal cells as well as tumor cells." (PMID 28894755, 2017). "In 2010, researchers discovered that a cellular protein called cereblon (CRBN) is associated with thalidomide’s teratogenicity and that CRBN is also required for the anti-tumor effects of lenalidomide and similar drugs, as well as the development of resistance to this class of drugs." (PMID 23915913, 2013). "The potential deletion of the drug-binding region may lead to a direct loss of drug-binding function of CRBN; however, it is unclear if the relative amount of full-length CRBN present in the tumor cells may be sufficient to confer drug sensitivity, especially for a more potent compound." (PMID 35222546, 2022). "Another study showed other mutations in CRBN in MM patient who was initially responsive to thalidomide and lenalidomide treatment, who acquired resistance to lenalidomide over the disease course, and who was finally unresponsive to pomalidomide treatment at the time of tumor sampling." (PMID 36387095, 2022). "When combined with standard agents such as daratumumab, pomalidomide, or cereblon E3 ligase modulatory drugs, forimtamig has shown improved tumor clearance and reduced relapse rates." (PMID 42254134, 2026). "Most reported PROTACs recruit ubiquitously expressed E3 ligases, such as cereblon and the von Hippel-Lindau tumor suppressor." (PMID 41279184, 2025). "This is further supported by TCGA data that indicates the elevated expression levels in tumor tissue as a differentiating characteristic compared to CRBN, the most-frequently pursued E3 ligase for TPD applications." (PMID 38926334, 2024). "The anti-tumor effects induced by LEN are mediated through the modification of the target specificity of CRBN, an E3 enzyme responsible for ubiquitinating IKZF1 and IKZF3 in MM cells, as well as casein kinase 1 alpha (CK1α) in 5q-MDS." (PMID 38344143, 2023). "Since the anti-tumor effects of IMiDs are exerted through the E3 enzyme CRBN, lentivirus vector-based gene knockdown (KD) for CRBN was induced in LEN-sensitive HuT102." (PMID 38344143, 2023). "What is the right balance between the two CRBN isoforms inside tumor cell needed for achieving a good response?" (PMID 37815734, 2023). "Since lenalidomide is a cereblon‐targeting (CRBN‐targeting) drug, comparing CRBN expression in MDSCs from naïve and tumor‐bearing individuals is necessary." (PMID 37547175, 2023). "For instance, in IMiD-resistant tumor cells, the levels of CRBN are reduced; however, residual CRBN levels in LEN-resistant cells have been shown to be sufficient for POM to maintain functionality." (PMID 33916376, 2021). "HDAC inhibitors reduced tumor growth by downregulating c-Myc in a CRBN-independent manner, while upregulating MICA expression and, thus, enhancing the efficacy of immunotherapy." (PMID 33757580, 2021). "Contemporary understanding of IMiD biology indicates that these tumor cell intrinsic effects, and the broader microenvironmental and immunomodulatory activities, are underpinned by a direct interaction with CRBN." (PMID 34834536, 2021). "Since the discovery of the primary target protein of thalidomide, cereblon (CRBN), in 2010, novel molecular mechanism of how these IMiDs execute the anti-tumor activity has been vigorously investigated." (PMID 34680233, 2021). "Recently, cereblon (CRBN) is identified as a primary target that directly binds IMiDs and mediates the teratogenic and anti-tumor activities." (PMID 32984863, 2020). "The first mechanism of resistance to IMid compounds described in MM was a downregulation of CRBN expression in tumour cells." (PMID 29348877, 2017). "Although CC-885 is able to induce CRBN-mediated degradation of Ikaros, its anti-tumour properties stem from de novo interactions between CRBN–CC-885 and the translation termination factor GSPT1." (PMID 29118097, 2017).
tumor (continued). "Conversely, cereblon-recruiting PROTACs have lower molecular weights, allowing for oral bioavailability, but cereblon shows ubiquitous expression in normal and tumor tissues, which may limit the tumor selectivity of this class of PROTACs." (PMID 38791105, 2024). "Therefore, it is necessary to develop new ligands for Ub ligases other than CRBN and Von Hippel-Lindau Tumor Suppressor for designing PROTACs." (PMID 38582446, 2024). "IMiDs then execute their anti-tumor effect by competitively blocking this function of CRBN." (PMID 35454812, 2022). "Overall, these results suggest that CRBN expression might be in volved in suppression of tumor progression in KIRC." (PMID 33916291, 2021). "Serum CRBN levels were likewise raised in our patients with high LDH (r = 0.486, p = 0.001), a marker of high tumor burden and aggressive disease." (PMID 40650115, 2025). "For its part, Len targets the Cereblon (CRBN) component of an E3 ubiquitination complex, provoking the selective degradation of the tumor pro-survival transcription factors IKZF1s, and leading to MM cell cycle arrest and apoptosis." (PMID 36776330, 2023). "It binds CRBN to degrade IKZF1 and IKZF3, triggering apoptosis of DLBCL cell lines and blocking tumor growth in xenograft mouse models." (PMID 36499765, 2022). "They deciphered functional hotspots in the E3 ligases CRBN and VHL that tumor cells can use to evade degrader molecules." (PMID 36499765, 2022). "Moreover, the absence of CRBN mutations in all publicly accessible tumor samples from SCLC patients—a major subgroup of NE cancers—further supports the notion that this patient population may be largely free from resistance mechanisms associated with CRBN mutations." (PMID 40551250, 2025). "We would like to point out that all the effects including those on tumor-specific T cell responses that we observed here appear to be independent of the known IMiD target cereblon which is an E3 ligase component of the ubiquitin system." (PMID 38646638, 2024). "This can be achieved pharmacologically by applying PROTACs that target BCL-XL for ubiquitination (and thereby for proteasome-mediated degradation) within the tumor microenvironment, but these PROTACs cannot eliminate platelets because the expression of VHL or CRBN in platelets is minimal." (PMID 33627663, 2021). "Intriguingly, a greater reduction in tumor xenograft burden was observed when combining PROTAC 008 treatment with FER knockdown, possibly due to the off-target degradative activity of PROTAC 008 on other kinases such as AAK1 and GAK or the PROTAC-mediated inhibition of cereblon." (PMID 38791105, 2024). "Recently, cereblon was identified to be the target structure of lenalidomide and pomalidomide, and the subsequent enhanced degradation of cereblon-binding proteins like Ikaros, Aiolos and KPNA2 is responsible for the anti-tumor and immunostimulating effect of lenalidomide and pomalidomide." (PMID 29228683, 2017). "Although CRBN is primarily an intracellular protein without a classical secretion signal, its presence in serum may result from passive release due to increased tumor cell turnover or apoptosis, or from active export via non-classical mechanisms such as exosome cleavage." (PMID 40650115, 2025).
hematologic malignancies (5 papers, 2021 to 2025). "This strategy of using CRBN modulators as “molecular glues” that mediate the interaction between CRBN and neosubstrates is applied to the treatment of hematologic malignancies." (PMID 39117611, 2024). "LEN-induced efficacy for several hematological malignancies was rationalized with modulation of the target specificity of E3 enzyme CRBN." (PMID 38344143, 2023). "Here, we review the physiological activities of CRBN and how these may be modulated by CRBN-interacting small molecules (CISMs) to improve precision in the treatment of hematological malignancies." (PMID 34834536, 2021). "By binding cereblon (CRBN), thalidomide can activate the E3 ubiquitin ligase CRL4CRBN-mediated ubiquitination and degradation of the IKAROS family transcription factors IKZF1 and IKZF3, which play key roles in the tumorigenesis and progression of hematologic malignancies." (PMID 34530760, 2021).
infection (5 papers, 2016 to 2026). The state of being infected such as from the introduction of a foreign agent such as serum, vaccine, antigenic substance or organism. "Adding dTag1 degrader to HCMV UL87HF-infected HFF for 6 h in late infection depleted the UL87 LTF via the host proteasome after dTag1 joins the FKBP12F36V segment of the chimeric UL87 LTF to the host cereblon E3 ligase complex." (PMID 34339482, 2021). "Next, we generated reconstituted cell lines stably expressing AGIA-AirID-CRBN-WT (wild type) or -YW/AA by infection of CRBN−/− HEK293T cells with lentivirus, and we performed STA-PDA using the reconstituted HEK293T cells transiently transfected with Myc-SALL4 and Myc-IKZF1 expression vectors." (PMID 35013300, 2022). "The infection of My5 cells with lentivirus vector did not alter the sensitivity to lenalidomide, whereas expression of the His-tagged CRBN in My5 cells increased the sensitivity to IMiD, suggesting that His-tagged CRBN is functional." (PMID 27142104, 2016).
neurodevelopmental disorder (4 papers, 2016 to 2025). A behavioral and cognitive disorder with onset during the developmental period that involves impaired or aberrant development of intellectual, motor, or social functions. "Among these, haploinsufficiency ofSETD5, BRPF1, CRBN, ATG7, SLC6A11, GRM7, and ARPC4has been linked to neurodevelopmental disorders and cognitiveimpairment." (PMID 40995453, 2025). "It will be of interest to examine the Lon protease function of CRBN in model animals and human subjects of neurodevelopmental disorders." (PMID 27417535, 2016). "Another study has linked a mutation on CRBN Cys394, another cysteine involved in the Zn finger, to an inherited neurodevelopmental disorder, which could be due to the lack of functional CRBN during developmental phases." (PMID 34373585, 2021).
Neurological Disorder (3 papers, 2009 to 2025). "Interestingly, recent studies showed a potential link between CRBN and neurodegeneration, suggesting that CRBN could be a potential therapeutic target for preventing neurological disorders." (PMID 41258141, 2025).
blood cancer (2 papers, 2023 to 2025). "CRBN mediated the antiproliferative effects of Len in blood cancer cells." (PMID 39881283, 2025). "Therefore, CRBN mediates the teratogenic effect of Thal and the anticancer effects of Len and Pom in blood cancer." (PMID 39881283, 2025).
hematological cancer (2 papers, 2021 to 2025). "Given the potent antitumor activity of MGD-A7 and MGD-C9 in multiple hematological cancer cells, we sought to explore the potential interaction modes between these compounds and the CRBN protein at the molecular level through molecular docking." (PMID 41050081, 2025).
metabolic disease (2 papers, 2017 to 2021). A congenital disorder (due to inherited enzyme abnormality) or acquired (due to failure of a metabolically important organ) disorder resulting from an abnormal metabolic process. "This led us to hypothesize that CRBN could be a potential therapeutic target for the treatment of metabolic disorders." (PMID 34073624, 2021). "In addition, cereblon also regulates the expression, assembly, and activities of other special proteins related to cell proliferation and metabolism, resulting in the occurrence and development of metabolic diseases." (PMID 28894755, 2017).